TNF (tumor necrosis factor)
Diseases named in the same sentence as TNF in open-access papers (continued):
Sharing a sentence is not in itself a finding about the gene and the disease.
infection (continued). "As one of the main cytokines in the cytokine storm, TNF-a is a marker of disease severity and may be associated with severe infection." (PMID 39967674, 2025). "For instance, active transcription is linked to the methylation of histone H3 on lysine 4 (H3K4me3), and its presence at loci encoding pro-inflammatory molecules like TNF-α and IL-6 and cytokine gene loci like those encoding IFNs can increase their expression during infection." (PMID 40969755, 2025). "In addition to cell death, LF82 infection resulted in secretion of proinflammatory cytokines IL-1β, IL-6, IL-8, and TNF-α, indicating a causative or at least exacerbating role of AIEC in CD." (PMID 41163391, 2025). "A low FT3 state has been linked to impaired immune cell function, resulting in increased production of pro-inflammatory cytokines such as TNF-α and IL-6, which can exacerbate systemic inflammation, compromise pulmonary defense barriers, and heighten susceptibility to infection." (PMID 41296678, 2025). "International consensus statements do not mandate antifungal prophylaxis for IL-12/23 inhibitors, reflecting comparatively low serious infection risks versus tumor necrosis factor-alpha (TNF-α) inhibitors; nonetheless, individualized risk assessment is advised." (PMID 41393055, 2025). "However, the clinical use of TNF-α inhibitors and tocilizumab is limited by their high cost and increased risk of infection." (PMID 41001030, 2025). "We assessed of the infection risk among the elderly with five different TNF-α inhibitors." (PMID 40371340, 2025). "TNF is associated with host protection and parasite elimination, being a key cytokine for M1 polarization, and for the formation and maintenance of granuloma, in which parasites are encapsulated, thereby controlling the infection." (PMID 40794782, 2025). "Infection with PLP1-deficient parasites resulted in drastically reduced TNF-α and IL-6, resolved infection-driven IFN-γ production, and failed to result in exaggerated cytokine and chemokine responses associated with proinflammatory overproduction and host mortality." (PMID 40166190, 2025). "However, an increased risk of infection, such as those caused by M. tuberculosis, has been reported previously in patients receiving anti-TNF treatment." (PMID 40064845, 2025). "While other markers like CRP may also be elevated in various inflammatory conditions, TNF-α is more closely associated with the presence of active infection." (PMID 41357523, 2025). "Its unique structure as a PEGylated Fab’ fragment lacking an Fc region may explain this advantage, as it avoids Fc-mediated immune effects contributing to infection risk with other TNF-α inhibitors." (PMID 40763141, 2025). "Furthermore, montelukast treatment substantially decreased serum levels of TNF-α and IL-6 following infection, thereby ameliorating infection-associated organ dysfunction caused by excessive inflammation." (PMID 41090944, 2025). "The use of TNF-α inhibitors increased the infection risk in older adults." (PMID 40371340, 2025). "While TNF-α inhibitors is clinically effective, there are concerns that it may increase the risk of infections due to its involvement in host defense." (PMID 40371340, 2025). "Moreover, the administration of anti-TNF antibodies, such as infliximab and adalimumab, has been associated with a reduced extent and duration of antibody protection after infection and/or vaccination, and an elevated incidence of breakthrough infections." (PMID 40573926, 2025). "To summarize, this data suggests that receptor-independent infection of endothelial cells by JEV-associated microglia may contribute to the disruption of the BBB in a TNF-dependent pathway." (PMID 40384979, 2025). "In the context of TNF-α blockade, such subtle laboratory changes may represent a blunted systemic inflammatory response, masking the severity of underlying infection." (PMID 41531628, 2025).
infection (continued). "However, it has been reported that type I IFN impairs host defense to infection with L. monocytogenes by apoptosis of T cells, loss of TNF-producing cells, and blocking of the responsiveness of IFN-γ." (PMID 40979681, 2025). "The dose of Fe needed to make it susceptible to infection, however, must be given at a level high enough to inhibit neutrophil and macrophage immunological responses as well as the synthesis of tumor necrosis factor alpha (TNF-α) and nitric oxide." (PMID 39692481, 2025). "It was observed that the risk of infection was increased by treatment with anti-TNF agents." (PMID 40236366, 2025). "TNF-α, associated with necroptosis and pyroptosis, raises questions about whether its rise results from alveolar cell death or infection, requiring further investigation." (PMID 40611327, 2025). "In such cases, biological therapies, including TNF-alpha inhibitors and interferon-alpha, may be considered, taking into account factors such as infection risk, tolerability, and reimbursement considerations." (PMID 41367023, 2025). "Thus, we chose etanercept as a control to compare the risk of infection and infestations between TNF-α different inhibitors." (PMID 40371340, 2025). "Interestingly, MRSA challenge in WT mice (F/F/S) significantly decreased the proportion of lung CD8+ T cells expressing IFN-γ and TNF-α compared with F/F infection, which further highlights the immune dysfunction caused by secondary MRSA infection." (PMID 40493422, 2025). "TNF‐α is often associated with infection or upper‐respiratory‐tract inflammation." (PMID 38572767, 2025). "In addition, our study revealed a differential association between TNF-α inhibitors and AEs from infections and infestations." (PMID 40371340, 2025). "As a result, we sought to examine the infection risk associated with TNF inhibitors using a real-world retrospective and pharmacovigilance investigation in order to identify medications with a reduced risk of infection and make medication recommendations for susceptible patients." (PMID 40371340, 2025). "However, TNF inhibitors were linked to increased infection rates (OR = 2.41, 95% CI: 1.17–4.96;p = 0.02)." (PMID 40546904, 2025). "At day 1 post-infection, most staining for TNF was associated with F4/80+ cells in the spleen." (PMID 40064845, 2025). "It was found that SIRT7-KO cells showed less cell damage infection, and significantly reduced expression of pro-inflammatory cytokines (IL-6, IL-8, TNF-α) upon GPS infection, suggesting that SIRT7 deficiency can suppress the occurrence of inflammation induced by GPS infection." (PMID 40636259, 2025). "Among these differentially expressed genes, twelve genes significantly influenced by infection were associated with tumor necrosis factor production, comprising eight upregulated and four downregulated in the infected group when compared to the uninfected group." (PMID 40906080, 2025). "However, the growing number of patients receiving TNF inhibitors has led to gradual observations of distinctions in infection risk among the five TNF inhibitors." (PMID 39070789, 2024). "In addition, TNF is a potent inflammatory cytokine crucial for the immune response to pathogenic infections." (PMID 39458388, 2024). "Although not efficacious for all patients, JAK1 or p19 inhibition, which modulate IFN pathways, may be effective in those anti-TNF nonresponders for whom clinical benefit outweighs infection-associated safety risks." (PMID 39438660, 2024). "Moreover, the 11 cytokines (i.e., SDF-1, SCYB16, sCD30, IL-11, IL-18, IL-8, IFN-γ, TNF-α, sTNF-R2, M-CSF, and I-309) were associated with the infection, mortality, disease progression and recovery, and long-term hospitalization." (PMID 38476443, 2024). "Other systematic reviews and meta-analyses also concluded that there might be an increased risk of postoperative infections when anti-TNF-treatment was given perioperatively." (PMID 38236926, 2024).
infection (continued). "Thus, chronic inflammation caused by aging or disease and associated with increased TNF induces AM dysfunction, contributing to the increased susceptibility to the infection of aged animals and people." (PMID 38459711, 2024). "Consequently, we aimed to assess the risk of infection associated with TNF inhibitors by network meta-analysis to select drugs with a lower risk of infection and provide medication suggestions for susceptible patients." (PMID 39070789, 2024). "In addition, we performed a detailed meta-regression analysis to assess the effects of the five TNF inhibitors on the risk of infection for various disease types, ages, and background therapies." (PMID 39070789, 2024). "However, Neven and collogues did show a slight infection risk increase in patients undergoing orthopedic surgery when taking TNF-α inhibitors." (PMID 39045331, 2024). "IL-1β, IL-6, and TNF-α are important pro-inflammatory factors in the body, while IL-10 is an important anti-inflammatory and immune-regulating cytokine, playing an important role in alleviating immune damage caused by infections." (PMID 38903796, 2024). "In addition, previous studies showed that strains of L. (V.)braziliensis less susceptible to NO presented higher infection rates and reduced levels of TNF-α production." (PMID 38985089, 2024). "The ability of Deer-RECs to downregulate CXCL8 and TNF expression early may be key to their ability to weather the cytokine storm associated with SARS-CoV-2 WA1/2020 infection." (PMID 38189329, 2024). "In summary, this network meta-analysis showed that both golimumab and etanercept might have a lower risk of infection compared with other TNF inhibitors." (PMID 39070789, 2024). "Taken together, these results indicate that anti-TNF-treated patients with IBD may be at elevated risk for infections with EG.5.1, BA.2.86, and related omicron subvariants following vaccination despite some risk reduction." (PMID 39066413, 2024). "We first assessed whether TNF loss affected BBB integrity to regulate leukocyte influx into the CNS during craniotomy infection." (PMID 39044282, 2024). "Attenuating NF-κB activation is critical because it induces the transcription of pro-inflammatory genes, including those encoding cytokines like TNF-α and interleukin-1 beta (IL-1β), which are pivotal in immunological and inflammatory responses, particularly during infection and trauma." (PMID 39599671, 2024). "Our research shows that infection of rabbits with L. europaeus/GI.1, and GI.2 genotypes causes an overexpression of two critical acute phase cytokines—IL-6 in all examined tissues and TNF-α (in the liver, lungs, and spleen)." (PMID 39273479, 2024). "The data have shown that UST could potentially offer a greater net benefit to patients with CD, compared to TNF-α antagonists and vedolizumab, owing to its lower risk of serious infections." (PMID 38455044, 2024). "Indeed, Ser/5-HT signaling fuels the infection of astrocytes by T. cruzi, a process potentiated by IFNγ and TNF and linked to a neurotoxic milieu enriched in NO and glutamate." (PMID 38776344, 2024). "Therefore, if a patient has any recent infection, or malignancy, or elderly (>65), vedolizumab is usually the preferred drug of choice for UC due to its minimal effect on the immune system and decreased risk of infections compared to TNF-alpha inhibitors." (PMID 39280117, 2024). "This may result from the suppression of TNF-α-mediated immune responses, likely increasing the risk of infection." (PMID 39070789, 2024). "In the present study, PDCoV HNZK-02-P150 infection could cause the higher levels of TNF-α in jejunal and colon tissues relative to those in the PDCoV HNZK-02-P5 group." (PMID 38349151, 2024).
infection (continued). "Specifically, Mmp-3 is transcriptionally upregulated in the hippocampus of infant rats with PM, and its proteolytic activity on the extracellular matrix and its ability to increase soluble Tumor necrose factor alpha (TNF-a) levels are associated with brain injury following infection." (PMID 39469711, 2024). "From this perspective, the increased levels of TNFα in ME/CFS might be seen as an anti-inflammatory response to an exacerbated immune response to an ongoing infection (caused by EBV or another virus) that initiated ME/CFS." (PMID 38256421, 2024). "The top five pathways associated with the acute stage of infection were cytokine–cytokine receptor interaction, TNF signaling pathway, phosphatidylinositol-4,5-bisphosphate 3-kinase-AKT (PI3K-AKT) signaling pathway, mitogen-activated protein kinase (MAPK), and NOD-like receptor signaling." (PMID 38399695, 2024). "In healthy individuals, SAA levels are low; however, infection by bacteria or viruses causes cytokines such as interleukin-1, interleukin-6, and tumor necrosis factor to prompt the liver to secrete SAA, leading to a significant increase in its levels within 8 to 12 h." (PMID 39039452, 2024). "In a meta-analysis study of the literature, a significant increase in circulating levels of IL-6 and TNF-a was found during infection with the bacteria, when it was also associated with GC, increased serum levels of IL-6 IL-7, IL-10, IL-12 and TNF-a were found." (PMID 38455038, 2024). "Moreover, a network meta-analysis indicated that certolizumab pegol and infliximab were associated with a higher risk of serious infection compared to other TNF inhibitors." (PMID 39070789, 2024). "In a study of severe burn injury, IL-10:TNF-α plasma levels measured shortly after burn trauma were directly correlated with burn size, the severity of the injury, and the susceptibility to repeat infections (≥3) during recovery." (PMID 37180165, 2023). "However, the World Health Organization has issued black box warnings about the risk of TB and other serious infections with TNF-α inhibitors." (PMID 38029150, 2023). "On the other hand, inflammatory factors such as IL-6 and TNF-α could affect the synthesis of albumin by hepatocytes, thus increasing the risk of infection and promoting the invasion and metastasis of tumors." (PMID 37495731, 2023). "A large study pooled the safety results of all three clinical trials and found that, while IV golimumab had a similar safety profile to other TNF inhibitors, cotreatment with methotrexate was associated with increased alanine transaminase levels and an increased incidence of serious infections." (PMID 37511975, 2023). "Whether anti-TNF is associated with an increased risk of infections is controversial, and newer biologics including vedolizumab and ustekinumab are thought to have a more favorable safety profile when treating elderly persons with IBD." (PMID 37674503, 2023). "The major cytokines involved in the APR include interleukin-6 (IL-6), interleukin-1β (IL-1β), and tumor necrosis factor-α (TNF-α), and these cytokines produce the clinical signs associated with inflammation or infection stimulate other cells in the APR cascade, and activate the production of APPs." (PMID 36670767, 2023). "Inflammation is a marker of numerous diseases and is associated with infection and the immune system, accompanied by the production of inflammatory mediators, the pro-inflammatory cytokines such as tumor necrosis factor-α (TNF-α), interleukin (IL)-1β, and IL-6." (PMID 37836464, 2023). "Also, this study implied a significant relationship between TNF-α serum levels and the severity of infection in heavily infected bladder tissue, indicating a strong association between antigens secreted by the trapped eggs and TNF-α serum levels." (PMID 37068081, 2023).
infection (continued). "Casp1/11/8–/–Ripk3–/– mice, however, should lack the cell death pathways initiated by NLRC4 (via Caspase-1 or Caspase-8), Caspase-11, and TNFα, and our results above suggest that these mice might be highly susceptible to infection." (PMID 36645406, 2023). "Limiting the immunomodulator comedication to IBD patients with immunogenic LOR to the anti-TNF monotherapy might be an alternative approach to initial combination therapy for all patients, especially when the risk of malignancy or infection is relevant." (PMID 36840779, 2023). "Additionally, although TNF antagonists have the potential to improve liver function, certain studies have also reported higher rates of infection and mortality associated with TNF therapy." (PMID 38268900, 2023). "In addition, other pathways that are linked with infection and host cell associations, such as adherens junctions, endocytosis, TNF signaling, and apoptosis, were identified." (PMID 37569480, 2023). "Moreover, the levels of pro-inflammatory cytokines IFN-γ, TNF-α, IL-1β, and IL-6 were significantly lower in the Δα-amy group, further suggesting that infection with Δα-amy cysts hardly caused remarkable inflammatory damage to intestinal tissues." (PMID 38087373, 2023). "However, mice starting high-dose anti-TNF therapy after they had established control were still susceptible to infection." (PMID 37233265, 2023). "In addition, other pathways that are linked with infection and host cell associations, such as adherens junctions, endocytosis, TNF signaling, the lysososme pathway, and TGF-β signaling, were also identified." (PMID 36768651, 2023). "Notably, viral miRNAs can bind to host miRNAs during the infection, targeting immunity-associated genes and affecting signaling pathways of tumor necrosis factor (TNF) and chemokines." (PMID 38140218, 2023). "Apart from this hypothesis, the immune response resulting from tissue damage or infection causes various kinds of leucocytes to produce proinflammatory factors like Tumor Necrosis Factor (TNF)-α or interleukin (IL)-6." (PMID 36765630, 2023). "The risk of infection also significantly increases when anti-TNFα therapies are combined." (PMID 37554981, 2023). "Such a combined strategy might help cope with various anti-TNF therapy-associated complications, such as the refractoriness of certain groups of patients, elevated infection rates, and high treatment costs." (PMID 36346114, 2023). "TNF-α is a potent protective cytokine that contributing to anti-viral and anti-bacterial responses during the early phase of infection, however, excessive production causes heightened lung immunopathology and inflammation, particularly in the late phase of infection." (PMID 38075899, 2023). "Notably, TNF inhibitor–treated patients have an increased risk of S. aureus skin colonization and infection, suggesting the involvement of TNF in protection against S. aureus in the skin." (PMID 37327341, 2023). "Indeed, in high-infected larvae, uncontrolled parasitaemia induces a strong pro-inflammatory response, defined by an overall induction of TNFα and IL1β in both immune and endothelial cells, associated with susceptibility to the infection." (PMID 36829432, 2023). "By inhibiting tissue necrosis factor (TNF), T cell activation is blunted, causing a decrease in cytokine release and inflammatory cell reactions, but this effect also causes undesirable immunosuppression and an increased risk for infections." (PMID 37511975, 2023). "However, the AG genotype was associated with a higher concentration of TNF-α that helps in the inhibition of viral replication and early control of the infection leading to a decrease in joint pain in individuals with chronic Chikungunya." (PMID 37703107, 2023). "Additionally, when using the IL-10:TNF-α ratio as a predictor for susceptibility to repeat infections, patients less susceptible to repeat infections (≤ 2) exhibited an average IL-10:TNF-α ratio of 5.0." (PMID 37180165, 2023).